Y_RNA (Y RNA )
Gene: Miscellaneous RNA gene on chromosome 12 (7,800,361 to 7,800,467, reverse strand). Ensembl gene ENSG00000199912.
Homologues: Orthologues: chimpanzee Y_RNA (98% identical). Paralogues in human: Y_RNA (85% identical), RNY1P5 (83% identical), Y_RNA (83% identical), Y_RNA (82% identical), Y_RNA (81% identical), Y_RNA (80% identical), RNY1P6 (79% identical), Y_RNA (79% identical), RNY1 (79% identical), Y_RNA (78% identical), Y_RNA (77% identical), RNY1P2 (76% identical), and 96 more.